DCAF5 (DDB1 and CUL4 associated factor 5)
Description:
Is a substrate receptor for the CUL4-DDB1 E3 ubiquitin-protein ligase complex (CRL4). The complex CRL4-DCAF5 is involved in the ubiquitination of a set of methylated non-histone proteins, including SOX2, DNMT1 and E2F1.
Synonyms: BCRP2; BCRG2; KIAA1824; WDR22; D14S1461E
Tractability: PROTAC: ubiquitination databases record sites on it; its protein half-life has been measured.
Gene: Protein-coding gene on chromosome 14 (69,050,881 to 69,153,179, reverse strand). Ensembl gene ENSG00000139990.
Subcellular location (Human Protein Atlas): Mitochondria
Pathways (Reactome):
Metabolism of proteins: Neddylation
Gene Ontology:
Molecular function: protein binding
Biological process: regulation of stem cell population maintenance; protein ubiquitination
Cellular component: Cul4-RING E3 ubiquitin ligase complex; Cul4A-RING E3 ubiquitin ligase complex; Cul4B-RING E3 ubiquitin ligase complex; nucleoplasm
Genetic constraint (gnomAD): Loss-of-function variants: 9 observed, 82.26 expected, observed/expected ratio (o/e) 0.11, 90% interval 0.065 to 0.19. The upper end of that interval is the gene's LOEUF score, 0.19, which puts it in group 1 of 6, group 1 being the genes least tolerant of losing a copy. Missense variants: 841 observed, 1,257.5 expected, observed/expected ratio (o/e) 0.67, 90% interval 0.63 to 0.71. Synonymous variants: 431 observed, 487.43 expected, observed/expected ratio (o/e) 0.88, 90% interval 0.82 to 0.96.
Homologues: Orthologues: chimpanzee DCAF5 (99% identical), macaque DCAF5 (99% identical), pig DCAF5 (95% identical), dog DCAF5 (95% identical), rabbit DCAF5 (93% identical), rat Dcaf5 (92% identical), mouse Dcaf5 (91% identical), guinea pig DCAF5 (85% identical), tropical clawed frog DCAF5 (64% identical), zebrafish dcaf5 (50% identical), Drosophila melanogaster CG42233 (28% identical), Caenorhabditis elegans R11D1.1 (15% identical). Paralogues in human: WDTC1 (12% identical), DCAF6 (12% identical), DCAF8 (12% identical), DCAF8L2 (11% identical), DCAF8L1 (11% identical).
Diseases named in the same sentence as DCAF5 in open-access papers:
DCAF5 is named in the same sentence as 13 diseases in open-access papers, as found by Europe PMC text mining. Sharing a sentence is not in itself a finding about the gene and the disease. The quoted sentences say what the papers report.
glaucoma (1 paper, 2025). Increased pressure in the eyeball due to obstruction of the outflow of aqueous humor. "Similarly, variant rs7144307 in DCAF5 (P-REECAP < 1.2×10−8) strongly colocalized with glaucoma (PP-H4 = 0.923) despite being subsignificant in the disease-label GWAS." (PMID 41332846, 2025).
neuropathies (1 paper, 2022). "Since we assume that NPY levels are diminished in the presence of NPY-LA, we hypothesize there is a possible association between NPY-LA levels, neuropathy, gene variants of DCAF5, and the function of ABCC2." (PMID 35627254, 2022). "Studies of NPY-LA with more participants having long-duration T1D and T2D and including identifications of genetic variants are needed to further elaborate associations between DCAF5, ABCC2, NPY-LA, and neuropathies." (PMID 35627254, 2022).
rhabdoid tumor (1 paper, 2025). An aggressive malignant embryonal neoplasm usually occurring during childhood. "The study found that rhabdoid tumors (RT), which are highly aggressive due to the loss of the key tumor suppressor protein SMARCB1, could be suppressed by the depletion of the quality control protein DCAF5." (PMID 40115023, 2025).
cancer (5 papers, 2024 to 2025). A tumor composed of atypical neoplastic, often pleomorphic cells that invade other tissues. "Recent data have shown that the gene DDB1-CUL4-associated factor 5 (DCAF5) is required for the survival of SMARCB1-mutant cancers and actually promotes the degradation of incompletely assembled SWI/SNF complexes in the absence of SMARCB1." (PMID 39125735, 2024). "Targeting DCAF5 can suppress SMARCB1-mutant cancer by stabilizing the SWI/SNF complex, underscoring the critical connection between CUL4B and the SWI/SNF complex." (PMID 40203790, 2025). "After depletion of DCAF5, SMARCB1-deficient SWI/SNF complexes reaccumulate, bind to target loci, and restore SWI/SNF-mediated gene expression to levels that are sufficient to reverse the cancer state, including in vivo." (PMID 39125735, 2024). "Therefore, the cancer is not caused by the loss of SMARCB1 function per se, but rather by DCAF5-mediated degradation of the SWI/SNF complex." (PMID 40115023, 2025). "Consequently, cancer results not from the loss of SMARCB1 function, but rather from DCAF5-mediated degradation of SWI/SNF complexes." (PMID 39125735, 2024). "The role of DCAF5 was confirmed by CRISPR-based competitive fitness assays and short hairpin RNA (shRNA)-mediated knockdown, showing that DCAF5 is required for the proliferation of SMARCB1-mutant RT lines, but not for cancer cells harbouring other SWI/SNF mutations." (PMID 39237495, 2024).
DCAF5 also shares sentences with these, for which no sentence is quoted: childhood cancer (1 paper); depression (1); infection (1); insomnia (1); Intellectual disability (1); psychiatric disorder (1); schizophrenia (1); vascular disorder (1); viral infection (1).